FH (fumarate hydratase)
Diseases named in the same sentence as FH in open-access papers (continued):
Sharing a sentence is not in itself a finding about the gene and the disease.
paraganglioma (45 papers, 2010 to 2025). A benign or malignant neoplasm arising from paraganglia located along the sympathetic or parasympathetic nerves. "This approach, termed metabologenomics, was already successfully used to identify SDH- and FH-deficient phaeochromocytoma and paraganglioma." (PMID 34822422, 2021). "Loss of function in both genes can be detected by metabolic screening, as SDH-deficiency leads to accumulation of succinate and FH-deficiency to accumulation of fumarate, as our group has previously shown for phaeochromocytoma/paraganglioma." (PMID 34822422, 2021). "Mutation of another important enzyme of the TCA cycle, fumarate hydratase (FH), which converts fumarate to malate, is also implicated in metastasis of pheochromocytoma and paraganglioma." (PMID 31849832, 2019). "A number of CPGs in which variants were identified, such as MAX and FH, have been relatively recently described as causing pheochromocytoma and paraganglioma." (PMID 29909963, 2018). "The accumulation of both fumarate and succinate in FH-mutated paragangliomas makes sense, as FH catalyzes the subsequent step in TCA." (PMID 29342092, 2018). "In another study that used 598 samples of paragangliomas/pheochromocytomas, mutations in FH were found in 0.83% of all the tumors, of which 60% of the FH-mutant tumors were malignant." (PMID 28187001, 2017). "An FH mutation associated with paraganglioma was first discovered in 2013 in one of 145 tumor samples exhibiting elevated methylation and no mutations in the SDHx genes." (PMID 28187001, 2017). "For example, risk for paraganglioma involves mutations in the succinate dehydrogenase gene, whereas risk for leiomyomatosis and renal cell carcinoma involves mutations in the fumarate hydratase (fumarase) gene." (PMID 20181022, 2010). "This strongly suggests that FH acts as a tumor suppressor gene in paragangliomas and may serve as evidence of variant pathogenicity." (PMID 38721148, 2024). "Heterozygous mutations in the fumarate hydratase (FH) cause FH tumor predisposition syndrome, an autosomal dominant condition with increased risk for uterine and cutaneous leiomyomata, renal tumors, and a lower risk of pheochromocytomas and paragangliomas." (PMID 38700789, 2024). "Intriguingly, ATRX mutations and ALT are also common in paragangliomas and pheochromocytomas, and these tumours have frequent mutations in Krebs cycle genes, such as fumarate hydratase (FH) and succinate dehydrogenase (SDHx), leading to an accumulation of fumarate and succinate." (PMID 33972520, 2021). "The sporadic loss of FH or transcriptional downregulation of FH was found in various cancers, such as pheochromocytomas, paragangliomas, neuroblastomas, adrenocortical carcinoma, ependymoma, osteosarcoma, bladder cancer, breast cancer, glioma, colorectal cancer, and testicular cancers." (PMID 32764295, 2020). "Germline VHL, SDHx and FH mutations may predispose to phaeochromocytoma/paraganglioma and RCC, and on rare occasions renal tumours have been reported in association with mutations in the phaeochromocytoma genes TMEM127 and MAX." (PMID 29680948, 2018). "Notably, oncogenesis under the conditions of FH deficiency follows a genetic pathway similar to that in malignant SDHB-mutant paragangliomas/pheochromocytomas." (PMID 28187001, 2017). "Indeed, we previously showed loss of 5-hmC in SDH mutant paragangliomas and FH mutant smooth muscle tumours, again verifying our methodology." (PMID 28484589, 2017). "Mutations in succinate dehydrogenase (SDH) and fumarate hydratase (FH) were found in diverse cancers including paraganglioma, pheochromocytoma, and papillary renal carcinoma." (PMID 36979633, 2023). "In contrast, we previously showed increased H3K9me3 in SDH mutant paragangliomas and FH mutant smooth muscle tumours using the same immunohistochemical methods." (PMID 28484589, 2017).
paraganglioma (continued). "Group I comprises subgroup 1A, including paragangliomas with mutations in the SDH and fumarate hydratase (FH) genes, and subgroup 1B, representing those with mutations in the HIF2A and VHL genes." (PMID 28187001, 2017). "These factors explain enrichment of TCA/mitochondrial lesions in specific tumor types (e.g., IDH-mutant glioma/acute myeloid leukemia, SDHx in pheochromocytoma/paraganglioma, and FH-deficient renal cell carcinoma) without implying a universal rule." (PMID 41154717, 2025). "A heterozygous missense variant in SLC25A11 (c.715C>A/p.Pro239Thr) was first identified in a 46-year-old patient with a non-secreting abdominal paraganglioma, which exhibited a cluster 1A molecular profile in the absence of pathogenic variants in SDHx or FH." (PMID 40242210, 2025). "In SDH mutant paragangliomas and GIST, and in FH deficient smooth muscle tumours, 5-hmC was low to absent." (PMID 28484589, 2017).
pheochromocytoma (39 papers, 2008 to 2026). "We detected an FH mutation frequency in HNPGLs of 0.66%, which is lower than that reported for PPGLs predominantly enriched with pheochromocytomas (PCCs)." (PMID 38721148, 2024). "Succinate dehydrogenase subunit B (SDHB) and fumarate hydratase (FH) staining were retained; however, weakly positive 2SC staining raised concerns for FH-deficient pheochromocytoma." (PMID 37908587, 2023). "Mutations in FH are associated with hereditary leiomyomatosis and renal cancer; additionally, mutations were also found in some pheochromocytomas that resembled SDH-mutant tumors in their transcription and methylation profiles." (PMID 28187001, 2017). "This has already been observed in pheochromocytomas and other tumor types, with mutations in IDH, FH, and SDH, in which DNA is globally hypermethylated, promoting a metastatic behavior." (PMID 38285158, 2024). "More recently, certain germline FH variants have been linked to pheochromocytoma (PHEO) risk in individuals without features of HLRCC." (PMID 42120995, 2026). "For the individual with FH and MAX variants, it is easier to attribute the diagnosed pheochromocytomas to the truncating MAX variant, but evidence for the role of FH in this tumor type is accumulating, and this variant could have contributed to tumorigenesis." (PMID 29909963, 2018). "Cluster 1 PPGLs include pheochromocytomas and abdominal paragangliomas carrying the highest risk of metastatic spread, especially the TCA cycle aberrant tumors carrying genetic variants in enzymes regulating the TCA cycle, including SDHA, SDHB, SDHAF2, FH, MDH2, ISH1 and SLC25A11." (PMID 35205664, 2022). "Accordingly, pheochromocytoma PC-12 cells showed a decrease in primary cilia expression under hypoxia (1% O2), and the same effect was observed with both the downregulation and the pharmacological inhibition of SDHB, and fumarate hydratase (FH)." (PMID 30884815, 2019).
Cutaneous leiomyoma (25 papers, 2008 to 2025). The presence of leiomyoma of the skin. "A skin biopsy confirmed cutaneous leiomyomas and subsequent genetic testing demonstrated a pathogenic heterozygous mutation on exon 7 of the FH gene, confirming a diagnosis of HLRCC." (PMID 38098923, 2023). "Her family history included uterine and cutaneous leiomyomas and a confirmed FH mutation in mother’s family." (PMID 31792767, 2020). "None of the 13 individuals presented with other typical features (cutaneous leiomyoma or renal tumors) of HLRCC besides their FH deficient ULs, indicating sporadic events." (PMID 32612247, 2020). "The FH mutation was initially detected in the girls’ mother who had cutaneous leiomyomas, and this specific mutation was previously published in a case series." (PMID 31792767, 2020). "Other clinical manifestations of HLRCC include multiple cutaneous leiomyomas in 73–100% of FH mutations carriers and uterine leiomyomas in ± 75% of female carriers." (PMID 31792767, 2020). "In this syndrome patients also develop multiple cutaneous leiomyomas in almost all cases and definitive diagnosis is only made by the presence of a germline mutation in the fumarate hydratase gene." (PMID 26301110, 2015). "Germline FH mutations have been identified in the vast majority of patients with multiple skin leiomyomas, and the relatives of probands have often been subsequently diagnosed with skin leiomyomas, suggesting that many more cases are currently going unrecognized." (PMID 18366737, 2008). "Cutaneous leiomyomas (CLMs) are associated with Hereditary Leiomyomatosis and Renal Cell Cancer (HLRCC) syndrome (Mendelian Inheritance in Man [MIM]: 150800)—a rare genodermatosis caused by a heterozygous pathogenic variant in the fumarate hydratase (FH) gene." (PMID 39896049, 2025). "Thus, the absence of cutaneous leiomyomas should not preclude consideration of HLRCC diagnosis when FH mutations are found on genetic carrier screening." (PMID 37663422, 2023). "The proband who carried FH mutation c.952C>T (p.His318Tyr) presented cutaneous leiomyoma and no UL." (PMID 26113603, 2015).
breast cancer (21 papers, 2009 to 2025). A primary or metastatic malignant neoplasm involving the breast. "In line with this, the presented case study involved a patient with TNBC, further supporting the relevance of FH deficiency in basal-like breast cancer." (PMID 41008787, 2025). "On the other hand, low ATM expression is found to be correlated with increased tumor-infiltrating CD8+ T cells in breast cancer and fumarate hydratase-deficient renal cell carcinoma." (PMID 37174688, 2023). "To test this idea, we examined the effects of ONC201 on renal and breast cancer cells that lack mtDNA or that have a mutation in FH, a protein essential to the tricarboxylic acid (TCA) cycle." (PMID 29719618, 2018). "Additionally, 1.05% of breast cancer (BC) patients (389 out of 36,966) have been found to carry FH pathogenic or likely pathogenic variants." (PMID 41008787, 2025). "This suggests that breast cancer may be particularly susceptible to perturbations in FH activity." (PMID 40721560, 2025). "In contrast, angiogenesis and epithelial–mesenchymal transition (EMT) pathways were upregulated, suggesting a potential benefit from targeting the VEGF pathway in breast cancer patients with FH aberrations." (PMID 41008787, 2025). "By studying thousands of breast cancer samples, we found that tumors missing FH tend to create a special environment that helps them grow and survive, especially by encouraging new blood vessel formation." (PMID 41008787, 2025). "Overexpression of FH has been reported to inhibit the progression of breast cancer and endometrial cancer." (PMID 41380966, 2025). "We analyzed FH aberrations across different cancer types using data from pan-cancer studies and breast cancer (BC) studies." (PMID 41008787, 2025). "Lastly, we analyzed the prognostic values of FH and the luminal genes in breast cancer based on The Cancer Genome Atlas (TCGA) database." (PMID 37592347, 2023). "Since many tumour suppressor genes are known to be inactivated by DNA promoter methylation, we examined promoter methylation of SDH and FH in a cohort of breast carcinomas." (PMID 19778456, 2009). "The identification of FH expression as a potential biomarker could help personalize anti-angiogenic treatment strategies in breast cancer patients, particularly those who currently lack effective targeted options." (PMID 41008787, 2025). "Bioinformatic interrogations point towards an amplification of FH in breast cancer that may reveal an FH dependency that can be targeted with HDAC6 inhibition." (PMID 40721560, 2025). "FH expression by breast cancer cells promotes tumor growth via immunosuppression and positively correlates with the presence of immunosuppressive macrophages, since FH directly promotes the differentiation of blood-derived monocytes into immunosuppressive macrophages." (PMID 38410512, 2024). "Additionally, FH expression was identified as an independent prognostic factor in breast cancer patients." (PMID 37592347, 2023). "No DNA methylation was identified in the promoter regions of the SDHA, SDHB, SDHC, SDHD and FH genes in 72 breast carcinomas and 10 breast cancer cell lines using methylation-sensitive high resolution melting which detects both homogeneous and heterogeneous methylation." (PMID 19778456, 2009). "Since HIF-1α is frequently expressed in breast carcinomas, DNA methylation at the promoter regions of the SDHA, SDHB, SDHC and SDHD and FH genes was evaluated as a possible mechanism in silencing of SDH and FH expression in breast carcinomas." (PMID 19778456, 2009). "In the context of brain-specific breast cancer metastasis, FH mRNA and protein expression was increased in 231-BR but not in 231-BR-2 cells (middle and right), thus disqualifying this enzyme as a shared metabolic sensor for brain tropism." (PMID 36139533, 2022). "Indeed, isocitrate dehydrogenase (IDH), succinate dehydrogenase (SHD), fumarate hydratase (FH) and ATP5B were all upregulated in human breast cancers with low stromal FAK." (PMID 32157087, 2020).
breast cancer (continued). "In conclusion, promoter methylation of the SDHA, SDHB, SDHC, SDHD and FH genes is unlikely to be an important mechanism in stabilising HIF-1 in breast carcinomas through the downregulation of the expression of SDH and FH genes." (PMID 19778456, 2009). "Increases in α-KG have been found to up-regulate succinate dehydrogenase (SDH) and fumarate hydratase (FH), reduce the onco-metabolites succinate and fumarate, and further stabilize HIF prolyl hydroxylase 2 (PHD2) and decrease HIF-1α, ultimately suppressing breast cancer metastasis." (PMID 34034721, 2021).
glioma (18 papers, 2014 to 2025). A benign or malignant brain and spinal cord tumor that arises from glial cells (astrocytes, oligodendrocytes, ependymal cells). "Since TET1 is responsible for the oxidation of 5mC to 5hmC and gliomas with loss of 5hmC expression have been reported to show nuclear exclusion of TET1 expression, we investigated this correlation in SDH and FH mutant tumors." (PMID 26472283, 2015). "By analyzing The Cancer Genome Atlas (TCGA) data, we found that OGDH mRNA levels were significantly downregulated in IDH-mutated gliomas compared with other TCA cycle enzymes, including citrate synthase (CS), succinate dehydrogenase complex subunit B (SDHB), and fumarate hydratase (FH)." (PMID 39872214, 2024). "Besides, we also found that ASL, ADSL, and FH promote the malignant phenotype in glioma patients, while SDHA inhibits malignant progression." (PMID 37786553, 2023). "Furthermore, we found that six downregulated genes, including pLCE1, PRPS2, FH, ASL, DTYMK, and CTPS1 were significantly increased in high-grade glioma tissues (p < 0.001)." (PMID 38438374, 2024). "In contrast, expression levels of enzymes involved in downstream metabolism of isocitrate, including IDH1, IDH2 and IDH3A, α-KGDH, succinate dehydrogenase (SDHB), fumarate hydratase (FH) and malate dehydrogenase (MDH2), were remarkably lower in IDH1MUT glioma versus IDH1WT glioma." (PMID 28467784, 2017).
renal tumor (18 papers, 2007 to 2025). "The methylation profile of these CIMP positive FH-deficient RCC clustered with the TCGA CIMP-RCC tumors in a combined analysis with all TCGA renal tumors." (PMID 36455002, 2022). "Positive nuclear and cytoplasmic 2SC staining and a loss of FH staining via immunohistochemistry have been shown to be highly specific in identifying HLRCC‐associated renal tumors." (PMID 32463173, 2020). "Immunohistochemical analysis of kidney tumors from two unrelated patients with the germline FH c.914T > C (p.Phe305Ser) variant revealed a loss of fumarate hydratase (FH) staining and positive S‐(2‐succino)‐cysteine (2SC) staining." (PMID 32463173, 2020). "Cascade FH mutation screening enabled the early diagnosis of a renal tumour in an asymptomatic parent of a child with fumarate hydratase deficiency, resulting in timely and possibly life-saving treatment." (PMID 28747166, 2017). "Although allelic loss appears to be the most common alteration, insertion and missense mutations have also been described in kidney tumours from patients with germline mutations of FH." (PMID 17211469, 2007). "Somatic genetic events inactivating the second FH allele in leiomyomas and kidney tumours have been identified." (PMID 17211469, 2007). "Next‐generation sequencing (NGS) analysis of the patient's renal tumor revealed the following heterozygous somatic alterations: FH (NM_000143 ‐ 1q43) intragenic deletion involving the loss of exon 1–2, KDM5C (NM_004187) exon 7 p.K289E (c.865A > G), and NUF2 (NM_031423) exon 8 p.S171C (c.512C > G)." (PMID 32463173, 2020). "FH-deficiency may activate the proto-oncogene ABL1 in kidney tumors, which may upregulate aerobic glycolysis via the mTOR/HIF1α pathway, being a promising target marker." (PMID 27556703, 2016). "Single pure low-grade FH-deficient renal cell carcinoma of the kidney is extremely rare, and the image structure of this tumor exhibits diverse manifestations, which needs to be differentiated from many renal tumors in clinicopathological diagnosis in order to prevent misdiagnosis." (PMID 39659780, 2024). "SDH-deficient kidney tumors are likely to be as sensitive to glucose as FH-deficient tumors and targeting the vasculature or glucose transport in these tumors may provide a novel approach to disrupt the fundamental metabolic machinery of these aggressive cancers." (PMID 24348776, 2014). "Tubulocystic growth patterns can be seen in many subtypes of renal neoplasm, including oncocytoma, acquired cystic disease-associated RCC, and fumarate hydratase-deficient RCC, and, depending on their associated tumor subtypes, their clinical courses differ greatly." (PMID 39703302, 2024). "Pathological features play a key role in the diagnosis of FH-deficient RCC, but more experience is needed with low-grade morphologic tumors, and immunohistochemistry is a useful tool to differentiate this tumor from other renal tumors." (PMID 39659780, 2024). "On CT and MRI, the majority of these masses had invasive features and could foreseeably appear similar to any advanced stage renal tumor, although there was no direct comparison between FH-RCC and non-FH deficient RCC made in this study." (PMID 33608050, 2021). "Although similar analysis of HLRCC kidney tumours does not yet exist, these findings certainly support the possibility that elevated fumarate levels may represent a chronic cellular response to impaired/absent FH activity." (PMID 17211469, 2007). "The number of genes within a panel may be as few as six (e.g. BAP1, FH, FLCN, MET, SDHB, and VHL genes) though commercial genetic testing companies may offer larger gene panels (18–30 genes but including some for non-RCC kidney tumours;)." (PMID 38802529, 2024).